ADIPOQ (adiponectin, C1Q and collagen domain containing)
Diseases named in the same sentence as ADIPOQ in open-access papers (continued):
Sharing a sentence is not in itself a finding about the gene and the disease.
Obesity (continued). "Variations in ADIPOQ are associated with obesity, type 2 diabetes (T2DM) and related phenotypes in several populations." (PMID 21219602, 2011). "First, the ADIPOQ and its receptor genes were newly found to play a role in carcinogenesis especially in obesity-associated malignancies." (PMID 22087284, 2011). "This study aimed to measure the association between the adiponectin, C1Q and collagen domain-containing (ADIPOQ) gene variants and obesity in Koreans." (PMID 21603224, 2011). "Since both insulin resistance and obesity genotypes were demonstrated associated with colorectal cancer risk, it was reasonable to believe the interactions between variants of ADIPOQ and its receptor genes played a role in carcinogenesis of colorectal cancer." (PMID 22087284, 2011). "Genetic polymorphisms in LD blocks of the AdipoQ gene, including the promoter region and the boundary of exon 2-intron 2, are associated with T2D, obesity, DN and insulin resistance." (PMID 20029651, 2009). "Genetic association studies have demonstrated that single nucleotide polymorphisms (SNPs) +45G15G(T/G) in exon 2 and +276G/T in intron 2 of the AdipoQ gene confer the risk susceptibility to the development of T2D, obesity and diabetic nephropathy (DN)." (PMID 20029651, 2009). "Similarly, for rs3774261, located in the 3′ region of ADIPOQ gene, the G/G genotype (risk genotype) conferred approximately 3-fold higher odds of obesity compared to the (A/G) genotype." (PMID 41598180, 2025). "The contribution of low-frequency and rare variants of the ADIPOQ gene are important for obesity." (PMID 37888112, 2023). "The ADIPOQ gene is located in region 3q27 of the chromosome and consists of three exons and two introns recognized as a susceptible locus for type 2 diabetes and obesity." (PMID 35436947, 2022). "However, analysis of multifunctional genes like that for ADIPOQ, which is involved in regulating fat metabolism and obesity-associated cognitive decline, requires multiple evidences for identification of their functional roles." (PMID 36114174, 2022). "The DNA hypermethylation of the ADIPOQ promoter has been previously linked with obesity and IR." (PMID 34207541, 2021). "Reduced HMW adiponectin, in the backdrop of obesity and ADIPOQ genetic variants might alter metabolic profile posing risk towards T2D." (PMID 32076038, 2020). "Therefore, the ADIPOQ is an important candidate gene, since it has already been associated with metabolic disorders, including arthritis, osteonecrosis and obesity in humans." (PMID 31888477, 2019). "Interestingly, the core variable species L. lactis was positively correlated with those genes such as AdipoQ, Irs1, Cd 36, and Pde3b involved in obesity associated pathways." (PMID 31708891, 2019). "Moreover, serum adiponectin concentrations are also highly heritable and are linked to ADIPOQ gene, underlining the relevance of studying ADIPOQ as the candidate gene for obesity and consequently MetS." (PMID 30265726, 2018). "However, replication and validation studies are necessary to confirm the role of ADIPOQ in the genetic susceptibility to obesity in different populations." (PMID 28947843, 2017). "Additionally, obesity was associated with higher ADIPOQ mRNA level in SAT compared to VAT (P = 0.014)." (PMID 29213336, 2017). "We also found that this ADIPOQ variant appears to be related to BMI only in normal weight subjects, and this association was not significant in obese or overweight subjects suggesting an obesity-gene interaction." (PMID 26290432, 2015). "ADIPOQ, an adipocyte secreted protein, was found to one of the most downregulated gene in our analysis and it’s lower expression levels have been shown to be associated with obesity, insulin resistance, and type 2 diabetes mellitus." (PMID 25923423, 2015). "We next determined whether LEP and ADIPOQ DNA methylation levels in adipose tissue and blood were associated with obesity-related complications including dyslipidemia, hyperglycemia and hypertension." (PMID 25929254, 2015).
Obesity (continued). "This suggests that epigenetic modifications at ADIPOQ gene locus are functional and could potentially be involved in the pathogenesis of impaired glucose tolerance and insulin resistance associated with obesity." (PMID 25929254, 2015). "In human ADIPOQ, intron 2 variation (rs17366743: c.214+276A/C) has been linked with promoter polymorphisms in the gene, including c.-11426A/G, c.-11377C/G and c.-11391G/A, and is associated with ADIPOQ levels in diabetes and obesity." (PMID 26610572, 2015). "Thus, this study aimed to perform an analysis of the association between the ADIPOQ gene and BMI, an index of obesity, whilst considering plasma adiponectin levels in a Korean population." (PMID 21603224, 2011). "The effect of the ADIPOQ gene on the risk of obesity may vary according to ethnicity, age, and he degree of obesity across populations." (PMID 21603224, 2011). "Previous studies have shown that obesity could potentially influence the activation of ADIPOQ and its receptor genes and subsequent cancer risk." (PMID 22087284, 2011). "Similarly, several genetic association studies of the adiponectin (ADIPOQ) gene in type 2 diabetes and obesity have been reported." (PMID 21079816, 2010). "Furthermore, TGFB1 has been implicated in adipose dysfunction under conditions of obesity, evidenced by the reduced expression of adipogenic marker genes (ADIPOQ) in mouse adipocytes treated with TGFB1 and increases in Tgfb expression in adipose tissue of obese mice." (PMID 38998107, 2024). "In our present study, the action of the adiponectin gene (ADIPOQ) promoter SNP −11391 G/A (rs17300539) has been demonstrated on the risk of metabolic syndrome presence, insulin resistance, hypertriglyceridemia, and low serum adiponectin levels in Caucasian patients with obesity." (PMID 38140287, 2023). "Therefore, speculation that the gene ADIPOQ (rs2241766) polymorphism might be associated with obesity is reasonable." (PMID 36117520, 2022). "Thus, abnormal AdipoQ signaling may induce obesity-mediated harmful effects on the CNS and increase the risk of cognitive impairment and AD." (PMID 33584324, 2020). "In accordance with this hypothesis, we have lately reported that placental ADIPOQ DNA methylation levels are impaired following exposure to maternal glucose 2 h post-OGTT at second trimester of pregnancy suggesting that ADIPOQ epigenetic profile can increase susceptibility to obesity in the newborn." (PMID 25929254, 2015). "For further characterization, we analyzed the expression of three marker genes for obesity, the pro-inflammatory cytokine Il6 and the adipokines Lep and AdipoQ, using RNAseq datasets of visceral AT and visceral adipocytes from lean and obese mice." (PMID 40498013, 2025). "In obesity, miR-193b is downregulated, and its reduced expression correlates with lower ADIPOQ mRNA and protein." (PMID 40565591, 2025). "This study aimed to explore the role of nine variants in the ADIPOQ gene in relation to PCOS in a Tunisian cohort, with a specific interest in their association with hypoadiponectinemia and obesity." (PMID 41598180, 2025). "The ADIPOQ protein levels in breast tumour tissue and adjacent breast adipose tissue were similar in both postmenopausal women with normal BMI and those with obesity." (PMID 41456223, 2025). "Recent studies have explored the effects of high-fat diets on gene expression in adipose tissue, revealing specific gene alterations that contribute to obesity and insulin resistance such as ADIPOQ, CD36, PPARG, and IL6." (PMID 40408066, 2025). "The APOM and ADIPOQ gene expression were measured in the adipose tissue from 267 individuals with obesity and a human adipocyte cell line." (PMID 38491190, 2024). "The top-altered proteins in our study include VPS13C, ADIPOQ, and IGKV1D-13 which can be used as biomarkers for obesity-related IR and to identify individuals with a future risk for T2D." (PMID 38672154, 2024).
Obesity (continued). "Regarding the protective role of AdipoQ for obesity and diabetes, it has been largely attributed to the central effects of AdipoQ on feeding control, which can lead to reduction in body weight and body adiposity with improvement in glucose homeostasis." (PMID 38027109, 2023). "Previous studies have reported a relationship among obesity, adiponectin (ADIPOQ), and diabetes in Saudi Arabia." (PMID 37238960, 2023). "AdipoQ is an adipokine with antidiabetic, anti-obesogenic, and anti-atherogenic actions and known to have a protective role for obesity, diabetes, atherosclerosis, and cardiovascular disease." (PMID 38027109, 2023). "These assays resulted in two distinct patterns for PKP2 gene expression, segregated by fat depot and the obesity state, and matching those of adipogenesis-regulated genes, such as ADIPOQ, PLIN1, and FASN." (PMID 37607954, 2023). "Other studies have linked obesity and weight change with CRP, APCS, ADIPOQ, C3 and other complement proteins, ORM1, and ORM222,34,36–38." (PMID 37794065, 2023). "RP11-20G13.3 is among the lncRNAs required to maintain PPAR, C/EBP, and ADIPOQ levels during adipogenesis and is differentially expressed in obesity." (PMID 35163268, 2022). "Other studies have suggested the relationship between RCC risk and polymorphisms in obesity-related genes, such as FTO and ADIPOQ, and genes in the mTOR signalling pathways." (PMID 35328822, 2022). "Finally, our results demonstrate that HS and metabolic-related syndromes such as MetS and obesity may share transcription profiles and suggest that adipokines may be potential biomarkers for this interaction; down-regulation of ADIPOQ may be associated with diseases’ co-occurrence susceptibility." (PMID 36291580, 2022). "Further obesity-related genes include MC4R, peroxisome proliferator-activated receptor gamma (PPAR-G), and both adipokine-encoding genes (LEP and ADIPOQ)." (PMID 35565885, 2022). "Overall, we report six genetic variants of ADIPOQ, FTO and LEPR genes as obesity-risk markers and a CETP gene variant as lean mass/obesity protective marker in studied Pakistani cohort." (PMID 36126070, 2022). "Previously, it has been reported that the genetic variants in ADIPOQ, CETP, FTO, LEP, and LEPR genes are strongly correlated with obesity and associated metabolic complications in different ethnicities of the world." (PMID 36126070, 2022). "Specifically, the secreted SPP1 and the nuclear PPARγ and FTO were included among the down modulated genes associated to severe obesity pathway after PBMCs treatment with EVOO, while ADIPOQ was up regulated." (PMID 36386923, 2022). "Our study discovers a novel key function for the TBX15 TF in trans regulating an adipose co-expression network of 347 adipose, mitochondrial, and metabolically important genes, including PPARG, KLF15, PPARA, ADIPOQ, and 35 obesity GWAS genes." (PMID 34340684, 2021). "Considering that serum ADIPOQ concentration and its skin expression were altered in obesity, these findings suggest that ADIPOQ’s effects on skin are at least in part regulated by the reduced expression of ADIPOR2." (PMID 34438765, 2021). "This work describes the evaluation of ADIPOQ and its receptors on the skin of obese dogs; our study aimed to detect the presence of ADIPOQ system in the skin and its variation in the obesity condition." (PMID 34438765, 2021). "Our study discovers a new key function for the TBX15 TF in trans regulating an adipose co-expression network of 347 adipose, mitochondrial, and metabolically important genes, including PPARG, KLF15, PPARA, ADIPOQ, and 35 obesity GWAS genes." (PMID 34340684, 2021). "Accordingly, ADIPOQ and ADIPOR2 expression in the skin appear negatively correlated with obesity in the same way as the serum ADIPOQ level." (PMID 34438765, 2021). "The Adiponectin (ADIPOQ) epigenetic status also has relationship with obesity, and association has been reported between LDL-cholesterol levels and DNA methylation of both LEP and ADIPOQ." (PMID 34552557, 2021).
Obesity (continued). "In the past two decades, many studies have explored the relationship between the abnormal expression of leptin and AdipoQ and various obesity-related cancers." (PMID 33256658, 2020). "The related genes of obesity (ADIPOQ, GCG, PCSK1N, TFAP2A, and PYY) were also found to play significant roles in the occurrence of some types of cancer (BRCA, COAD, and UCEC)." (PMID 33299884, 2020). "Adiponectin gene (ADIPOQ/APM1/GBP28) locus, 3q27, has been strongly associated with a variety of metabolic disorders like- impaired glucose tolerance, obesity, dyslipidemia and T2D5–7." (PMID 32076038, 2020). "The most contributing SNP to this consortium was rs1801253-ADRB1, as well as other obesity risk-associated SNPs (UCP2, ADIPOQ, LEP, MC4R, etc.)." (PMID 32398726, 2020). "It is known that adipose tissue in obesity secretes a high level of pro-inflammatory adipokines, such as leptin, TNFα and ILs, but few anti-inflammatory cytokines such as adipoQ." (PMID 31989870, 2020). "We analyzed the genotype of the ADIPOQ gene in controls and people with severe obesity investigating their distribution." (PMID 31547312, 2019). "Adiponectin (also known as Acrp 30, AdipoQ) is a 30-kd protein secreted by adipocytes that has received much attention in obesity with respect to regulating insulin sensitivity, energy balance and cellular metabolism." (PMID 30819183, 2019). "Several of these genes, like LEP, PPARA, PPARD, LPIN1, SREBP1, and ADIPOQ are described in obesity in both humans and mice." (PMID 31921306, 2019). "It seems that genes related to obesity pathology (FTO, ADIPOQ, and MC4R), in genomic research association, are related to metabolic aspects and BMI in PCOS patients." (PMID 32133054, 2019). "It has been shown that, in tissue samples, expression of LEP was higher while expression of ADIPOQ was lower in lipoma compared to normal adipose tissue, which is the expression pattern characteristic for obesity." (PMID 30544806, 2018). "This is the first study to document contribution of ADIPOQ variants and haplotypes with RPL, and also to underscore the contribution of obesity to genetic association studies." (PMID 29559003, 2018). "Polymorphisms of the APOB, APOE, ADIPOQ, PLIN4, and HSD11β1 genes are important examples of genetic causes associated with dyslipidemias and obesity." (PMID 30507998, 2018). "In obesity adiponectin serum concentrations correlated positively with ADIPOQ mRNA in subcutaneous adipose tissue (P = 0.005) and negatively with protein levels in visceral adipose tissue (P = 0.001)." (PMID 29213336, 2017). "The aim of the present study was to test the impact of common genetic variations in ADIPOQ, RARRES2, and PPARGC1 on obesity-related traits and susceptibility in a sample of adult subjects from Rio de Janeiro, Brazil." (PMID 28947843, 2017). "ADIPOQ levels in adipose tissue are negatively correlated with obesity through the modulation of lipid synthesis, glucose utilisation and fatty acid oxidation." (PMID 28604630, 2017). "SFZYD administration also significantly attenuated obesity-induced decreases in AdipoQ expression in AT." (PMID 28570676, 2017). "Nevertheless, we cannot exclude that higher ADIPOQ DNA methylation levels would have led to higher degree of obesity." (PMID 25929254, 2015). "In humans and mice, the expression of ADIPOQ in adipose tissue is negatively correlated with obesity." (PMID 26610572, 2015). "Obesity also affects the production of adiponectin (ADIPOQ), leptin and retinol binding protein 4 (RBP4)." (PMID 25938677, 2015). "In this population, only 2 of the 8 (25%) biological candidate genes (ADIPOQ and UCP3) were associated with obesity, although only ADIPOQ remained significant after adjusting for admixture." (PMID 23950976, 2013). "This study, performed in a homogeneous group of individuals, supported the significant role of ADIPOQ variations in conditions linked to T2DM and obesity, partly by replicating earlier findings, but also by discovering novel associations." (PMID 21219602, 2011).